IL6 (interleukin 6)
Diseases named in the same sentence as IL6 in open-access papers (continued):
Sharing a sentence is not in itself a finding about the gene and the disease.
renal fibrosis (153 papers, 2012 to 2026). A final common manifestation of a wide variety of chronic kidney diseases characterized by glomerulosclerosis and tubulointerstitial fibrosis. "Long-time exposure to IL-6 results in the loss of typical markers of RECs, contributing to renal fibrosis." (PMID 39749325, 2024). "For example, elevated levels of tumor necrosis factor-alpha (TNF-α) and interleukin-6 (IL-6) are closely associated with renal fibrosis, renal function decline, and the occurrence of albuminuria." (PMID 39491271, 2024). "In a murine model of cyclosporine A-induced kidney injury, Hmox1 deficiency was associated with an increased mortality rate, renal fibrosis, inflammation (as indicated by elevated levels of the cytokine interleukin-6) and apoptosis." (PMID 39728801, 2024). "In this case, angiotensin II infusion induces the expression of IL-6 leading to renal fibrosis, while, in IL-6 deficient mice, they remain resistant to kidney damage." (PMID 35054831, 2022). "In our study, in line with the infiltration of macrophages and up-regulation of IL-6, renal fibrosis is associated enhanced." (PMID 28697727, 2017). "It has been well established renal aging is associated with structural changes, such as, renal fibrosis, and that IL-6 and MCP1 are associated with many fibrotic diseases." (PMID 28099916, 2017). "RSV treatment significantly attenuates the damage of renal pathologic changes and inhibition of renal fibrosis, which is associated with down-regulation of macrophage accumulation and the expression of IL-6, ICAM-1 and MCP-1." (PMID 27129290, 2016). "Confirming our dose range experiments, X203 reduced AKI-induced loss of kidney mass, limited renal fibrosis, and improved renal function while lowering inflammatory (Tnfα, Il6, Ccl2, Ccl5, Il1β), fibrosis (Col1a1, Col1a2, Col3a1, Fn1, Acta2) and tubular damage (Kim1, Ngal) markers." (PMID 36470928, 2022). "The authors addressed the discrepancy in the literature concerning the role of IL-6 in renal fibrosis, pointing to the inadequacy of comparing wildtype and IL-6 knockout mice, due to loss of classical IL-6 signaling which is responsible for anti-inflammatory activity in injured tissues." (PMID 33668632, 2021). "However, it has also been implicated in later detrimental effects, namely renal fibrosis and glomerulosclerosis, through IL-6 formation and the release of VEGF and TGF-β1." (PMID 31150459, 2019). "Interestingly, the expression pro-inflammatory IL-6 was increased in IL-10 deficient mice, suggesting a crucial role for IL-10-induced IL-6 in the protection from renal fibrosis." (PMID 30315190, 2018). "Its renal protective role was associated with reduced renal fibrosis, decreased activation of Akt and JNK, decreased expression of TGF‐β and IL‐6, and notably suppressed HA deposition and expression of HA receptors, CD44 and RHAMM." (PMID 41042601, 2026). "This modulation improves intestinal barrier function, reduces pro-inflammatory cytokines such as TNF-α and IL-6, and effectively alleviates renal fibrosis." (PMID 41048436, 2025). "Adipocytes secrete inflammatory mediators such as tumor necrosis factor-α (TNF-α) and interleukin-6 (IL-6), which contribute to the irreversible progression of renal fibrosis." (PMID 41424782, 2025). "Increased renal fibrosis also coincided with increased renal inflammation and apoptosis as evidenced by increased macrophage infiltration and IL-6 expression in the kidneys of obese SSLepR rats vs. lean control rats." (PMID 41463113, 2025). "During kidney injury, Ccr2 participates in inducing the migration of monocytes to the site of damage, releasing TGF-β and IL-6, and promoting the progression of renal fibrosis." (PMID 40953007, 2025). "In the renal fibrosis model, cordycepin reduces the secretion of IL-6 in renal TECs by inhibiting DRP1-mediated mitochondrial fission, thereby inhibiting the activation of fibroblasts, and ultimately reducing renal interstitial fibrosis." (PMID 41451126, 2025).
renal fibrosis (continued). "The role of IL-6 in KDs is equally complex and important, and it participates in the development of various renal pathological states, including nephritis, renal fibrosis, and CKD." (PMID 38533318, 2024). "Due to the involvement of the IL-6/STAT3 pathway in renal fibrosis, the blockade of STAT3 phosphorylation is a promising therapeutic approach in the UUO model in vivo." (PMID 39684261, 2024). "IL11 is a close family member of IL6, which was found to be related to he renal fibrosis in our previous studies." (PMID 37853428, 2023). "Results from Western blot also showed a reduction in the expression of renal fibrosis-related proteins (αSMA, Fn-1, Col3a1) and inflammatory factors (IL-1β, IL-6, TGF-β) in the kidney of acetate-treatment group." (PMID 36922584, 2023). "Mitochondrial dysfunction activates inflammation through the mtDNA-cGAS-STING-NF-κB pathway in renal fibrosis, with higher levels of the proinflammatory cytokines IL-6, TNF-α and IL-1β." (PMID 36959860, 2023). "M1 macrophages can produce pro-inflammatory cytokines such as TNF-α, IL-1β, and IL-6, promoting the progression of renal fibrosis." (PMID 37861543, 2023). "Folate-deficient diets further elevated serum TC, LDL-cholesterol, IL-6, tumor necrosis factor (TNF)-α, MCP-1, TGF-β1, and leptin, but decreased IL-10 level, and thus exacerbated renal fibrosis." (PMID 37630806, 2023). "A previous study reports that IL‐6 trans‐signaling pathway plays an important role in the initiation and progression of renal fibrosis." (PMID 37525933, 2023). "Our data demonstrated that the levels of TNF-α and IL-6 were increased in the kidney homogenate of DKD model mice, and the alteration was associated with the severity of renal fibrosis." (PMID 36448056, 2022). "Recently, a large body of experimental evidence suggested that IL-6 plays a role in renal fibrosis, although this finding remains controversial." (PMID 36147459, 2022). "Similar to the case in renal fibrosis, in our model system, it is most likely that IL6, along with other proinflammatory cytokines, boosted JAK/STAT signaling, which cooperated with the TGFβ/SMAD pathway to regulate the expression of fibrotic genes." (PMID 35288649, 2022). "The results showed that AMSCs decreased Scr, M1 macrophages, M1/M2 macrophages, TNF-α, IL-6, IL-1β, and renal fibrosis and increased IL-10 and the number of M2 macrophages." (PMID 34112221, 2021). "Our results suggested that IL-6 affects renal fibrosis by acting on IL6ST in DN progression, and the IL6ST/STAT3/NF-kB signaling pathway plays an important role in DN progression." (PMID 33995063, 2021). "Several previous publications have highlighted that SKI retarded renal fibrosis by inhibiting levels of interleukin-6, interleukin-1β, and TNF-α and modulating TGF-β1/Smad3 and JAK2/STAT3 signaling pathways." (PMID 35002735, 2021). "The pathological aspects of PNS were characterized in TGF-β signaling-engaged renal fibrosis, and renal inflammation with IL-6 expression in kidney." (PMID 33260558, 2020). "Inflammatory cytokines, such as tumor necrosis factor-α (TNF-α), interleukin-1β (IL-1β), and IL-6, can directly mediate renal fibrosis through inflammatory infiltration, fibroblast activation and synthesis and degradation of ECM." (PMID 32372953, 2020). "In the experiment with IL-6 knockout mice, IL-6 was the key regulator for exacerbation of albuminuria and renal fibrosis." (PMID 32961903, 2020). "Another study performed by Xia’s group showed that high extracellular levels of adenosine and the activation of its A2B receptor mediate the production of IL-6 and thereby promote renal fibrosis during CKD." (PMID 32340145, 2020). "A recent study showed that miR-410-3p attenuated renal fibrosis in lupus nephritis mice via directly targeting IL-6." (PMID 30242542, 2019).
renal fibrosis (continued). "In agreement with previous studies showing that the inhibition of EMT prevents the loss of RTEC transporters and inhibits inflammation, deletion of RUNX1 promoted SLC22A6 expression and inhibited IL-6 expression in renal fibrosis." (PMID 29759484, 2018). "In our study, JYYS granule significantly attenuates renal pathologic injury and renal fibrosis by downregulating the expression of IL-6, TNF-α, ICAM-1, and MCP-1, which were obviously higher in the SHR group than in WKY rats." (PMID 30598687, 2018). "One of the products of EPC is leukemia inhibitory factor, which itself activated the STAT3 pathway and mitigated formation of myofibroblasts, whereas a more potent gp130/STAT3 agonist, a fusion protein hyper‐IL‐6, also prevented renal fibrosis." (PMID 28297566, 2017). "On the other hand, a receptor‐independent inducer of gp130/STAT3 pathway, hyper‐IL‐6, is capable of consistently inducing in vitro pluripotency transcription factors, Nanog and c‐Myc, and later on Oct4, and preventing renal fibrosis in vivo." (PMID 28297566, 2017). "Other investigators observed that in a model mimicking the Alport’s syndrome (COL4A3−/− mice), deletion of DDR1 delays renal fibrosis via inhibition of NF-κB, IL-6 and TGF-β signaling." (PMID 26880216, 2016). "The depletion of macrophages induced by the liposome clodronate injection improved renal fibrosis with a reduction of kidney IL-6, type IV collagen, and TGF-β levels." (PMID 26630505, 2015). "The only available evidence of this link in the kidney was published recently in a study demonstrating that mice with genetic blockade of IL6 were protected against the development of renal fibrosis." (PMID 23883183, 2013). "We found that interleukin 6 was induced in the kidney in a murine model of renal fibrosis induced by unilateral ureteral obstruction." (PMID 23272241, 2012). "In the present study, we investigated the role of IL-6 in a murine model of renal fibrosis induced by unilateral ureteral obstruction (UUO) using IL-6 knockout (KO) mice." (PMID 23272241, 2012). "Additionally, the anti-inflammatory effects of these herbs become more pronounced at higher doses, as they suppress key inflammatory mediators such as TNF-α, IL-6, and NF-κB, which play a role in renal fibrosis and glomerular injury." (PMID 40151690, 2025). "Together, these immunological imbalances contribute to persistent activation of lymphocytes and macrophages, promoting the release of proinflammatory cytokines such as tumor necrosis factor-alpha (TNF-α) and interleukin-6 (IL-6), which directly contribute to glomerular injury and renal fibrosis." (PMID 41171774, 2025). "Besides, activated FoxO3 decreases IL6 levels via decrement of gene expression and protects against renal fibrosis." (PMID 39906624, 2025). "Besides, IL-6 mediates signaling crosstalk between ferroptotic kidney cells and surrounding fibroblasts, accelerating renal fibrosis." (PMID 39749325, 2024). "Additionally, angiotensin II is known to induce pro‐inflammatory factor IL‐6 production, while aldosterone stimulates ROS production, increasing endothelial cell permeability and promoting renal fibrosis." (PMID 39533116, 2024). "Animal studies further confirm the role of IL-6 in renal fibrosis and diabetic kidney injury." (PMID 39749325, 2024). "In renal fibrosis, the increased secretion of interleukin-6 (IL-6) exacerbates renal inflammation." (PMID 39769044, 2024). "Furthermore, IL-6 released by RTECs promotes the proliferation of adjacent fibroblasts and the excessive production of fibrotic matrix, accelerating renal fibrosis progression." (PMID 39749325, 2024). "Collecting evidence demonstrated that the infiltration of inflammatory cells, and accompanied by increased expression of monocyte chemoattractant protein-1(MCP-1), interleukin 1β (IL-1β), tumor necrosis factor α (TNF-α), and interleukin 6 (IL-6) are involved in the renal fibrosis process." (PMID 38972937, 2024).
renal fibrosis (continued). "Interestingly, TMAO was also able to significantly induce IL-6 release alone from renal fibroblast, strengthening the link to renal fibrosis." (PMID 38643262, 2024). "IL-6 knockdown markedly reduces renal fibrosis in type 1 diabetic mice." (PMID 39749325, 2024). "Second, IL-6 trans-signaling may be a crucial factor in the development of renal fibrosis, thus influencing the width of the GBM in the pathogenesis of diabetic glomerulopathy." (PMID 36776877, 2023). "Coppock and other scholars clarified that basophils are the main source of IL-6 in renal fibrosis." (PMID 38152332, 2023). "Blockade of IL‐6 trans‐signaling prevents renal fibrosis by suppressing STAT3 activation." (PMID 37525933, 2023). "Simultaneously, targeting IL-6 trans-signaling, Fc-gp130, could be a novel therapeutic strategy for renal fibrosis." (PMID 36776877, 2023). "In addition, immunological effects of VD and VD analogs have been reported in mouse models of renal fibrosis and obstructive nephropathy, such as a reduction of IL-6 and IL-1β in the kidney and reduced T cell and macrophage infiltration." (PMID 36505422, 2022). "Moreover, Il-6 can trigger TECs to generate collagen and accelerate interstitial fibrosis, which is also associated with enhanced STAT3 activation 11; while blocking Il-6 protects against IR-induced renal fibrosis by suppressing STAT3 activation." (PMID 35664078, 2022). "As CKD fibrosis progresses, senescent cells express and secrete pro-fibrotic factors (TGF-β, CTGF, and so forth) and pro-inflammatory factors (IL-1β, IL-6, TNF-α, and so forth), which are senescence-associated secretory phenotype factors, thereby accelerating renal fibrosis." (PMID 35227255, 2022). "Interestingly, the blockade of IL-6 trans-signaling attenuates renal fibrosis and inflammation in the UUO model of kidney fibrosis." (PMID 35806457, 2022). "Evidence has demonstrated that interfering with IL-6 trans-signaling could attenuate renal fibrosis via suppressing STAT3 activation while inhibiting the recruitment of macrophages." (PMID 35784347, 2022). "Recent studies have shown that overexpression of IL-6 and its receptor reduces the abundance of FN and Col IV in RMCs; IL-6 trans signal transduction may be involved in the occurrence and development of renal fibrosis." (PMID 33959133, 2021). "Accumulating evidence also demonstrated that the nephroprotective effects of quercetin are related to inhibiting renal tubular epithelial-mesenchymal transition and renal fibrosis and reducing the production of cytokines in DN, including IL-6, TNF-α, and IL-1β." (PMID 34349833, 2021). "Mechanistically, several preliminary studies have revealed that SKI alleviated CKD and renal fibrosis by inhibiting pro-inflammatory cytokines such as interleukin-6, interleukin-1β, and tumor necrosis factor-α (TNF-α) expression and modulating TGF-β1/Smad3 and JAK2/STAT3 signaling pathways." (PMID 35002735, 2021). "Furthermore, Epithelial-mesenchymal transition (EMT) and Endothelial-mesenchymal transition (EndMT) caused by the higher levels of IL-6, IL-1β and TGF-β are the key mesenchymal inducers that play important roles in the renal fibrosis." (PMID 34054555, 2021). "This study found that AOE could significantly improve the renal function, inhibit the IL-6 expression, lower the level of blood glucose and ameliorate renal fibrosis and inflammation." (PMID 32660472, 2020). "In addition, RKT significantly restored the Ang II-induced alteration in the expression of renal fibrosis- and inflammation-related genes such as type 3 collagen, transforming growth factor-β, monocyte chemoattractant protein-1 and interleukin-6." (PMID 30996242, 2019). "Therefore, APE1 suppressed renal fibrosis, not only via antioxidant and DNA-repair functions, but also partly by modulating the immune system through multiple pathways including Il6, Tnf, and chemokine families." (PMID 31127150, 2019).
renal fibrosis (continued). "However, cGKI‐KO‐kidneys revealed no more pronounced fibrosis compared to wt‐kidneys suggesting that other signalling pathways as IL‐6 are important for induction of renal fibrosis." (PMID 28396839, 2017). "In addition, recent studies have shown that IL-6 expression is up-regulated in renal fibrosis in mice and that this cytokine can induce the expression of collagen I." (PMID 28190086, 2017). "In summary, these studies, through the evolution from EPC extract to LIF and then to hyper‐IL‐6, demonstrate the instructive role of microenvironmental cues and may provide in the future a facile strategy to prevent and reverse renal fibrosis." (PMID 28297566, 2017). "SalB also reduces the expressions of inflammatory factors, such as interleukins (IL-1β, IL-6, and IL-8), alleviates apoptosis of vascular cells to improve heart function, reduces liver and renal fibrosis via down-regulating transforming growth factor β1 (TGF-β1) and depressing MMP-2 activity." (PMID 27893819, 2016). "One recent study showed that T lymphocytes and IL-6 play important roles in renal fibrosis." (PMID 25525413, 2014). "However, current evidence for a possible role of IL6 in the development of renal fibrosis is limited." (PMID 23883183, 2013). "Therefore, we investigated if interleukin 6 play a role in the recruitment and maturation of bone marrow-derived fibroblast precursors in the kidney during the development of renal fibrosis." (PMID 23272241, 2012). "TH17 cells that respond to IL-6 may be downstream mediators of basophils in renal fibrosis." (PMID 38152332, 2023). "Additionally, the roles of IL-6 were reported in several kidney diseases and targeting IL-6 could protect against renal fibrosis by suppressing STAT3 activation." (PMID 34884542, 2021). "Furthermore, three miRNAs have been associated with renal fibrosis in LN patients: miR-410, which contributes to renal fibrosis by inhibiting interleukin-6, miR-29c as predictor of early renal fibrosis, and miR-150, which promotes renal fibrosis by downregulation of SOCS1." (PMID 31349698, 2019). "Specifically, this group identifies the induction of IL-6 downstream of A2B adenosine receptor activation as a contributing candidate for the observed renal fibrosis, although it has also been demonstrated that mice deficient in IL-6 are not protected from developing renal fibrosis." (PMID 27579027, 2016). "Since IL-6 does not regulate the accumulation and activation of bone marrow-derived fibroblasts in the kidney in response to obstructive injury, we then examined if IL-6 deficiency has an effect on the development of renal fibrosis." (PMID 23272241, 2012). "Beyond these indirect pathways, visceral adiposity itself promotes a proinflammatory state (marked by TNF-alpha, IL-6, MCP-1) that drives renal fibrosis and activates the renin-angiotensin-aldosterone system, leading to glomerular hyperfiltration." (PMID 40834423, 2025). "By influencing the linoleic acid metabolism of this specific cell subset, it promotes the production of cytokines such as IL‐6, IL‐23, and TGF‐β, which exacerbate renal fibrosis, thus enabling the liver to regulate the kidneys." (PMID 40995682, 2025). "M1 macrophages, prevalent in DN, initiate inflammation, tissue damage, and renal fibrosis via proinflammatory cytokines such as TNF-a, IL-6, IL-10, and monocyte chemoattractant protein 1 (MCP-1)." (PMID 41438111, 2025). "In a model of kidney fibrosis, it has been suggested that basophil-derived IL-6 contributed to enhanced Th17 cell differentiation from CD4+ T cells, which contribute to renal fibrosis." (PMID 38780542, 2024). "Elevated levels of interleukin-1 (IL-1), interleukin-6 (IL-IL6), and other inflammatory markers in patients with CKD activate the inflammatory cascade, exacerbating renal damage and promoting renal fibrosis." (PMID 39371339, 2024).